CD69 (CD69 molecule)
Diseases named in the same sentence as CD69 in open-access papers (continued):
Sharing a sentence is not in itself a finding about the gene and the disease.
infection (continued). "Importantly, at both periods of infection an increased number of activated CD4+CD25+ and CD8+CD69+ T cells were found in the lungs of Treg depleted mice." (PMID 30410119, 2018). "To identify a set of activation markers associated with IAV‐specific CD8+ T cells during the initial phase of the immune response, we assessed the expression of CD25, the active form of CD43, CD69, and CD62L on DbPA224‐specific CD8+ T cells in the MLN, 5 and 6 days following HKx31 infection." (PMID 29972699, 2018). "Based on these TLR7-dependent changes observed in the lung in the early phase of IAV infection, we further assessed the kinetics of NK cell activation at the site of infection by analyzing lung NK cells from IAV-infected WT and TLR7ko mice for the expression of the early activation marker CD69." (PMID 29497422, 2018). "Overall, our results regarding CD69, CD27, and CD11b expression on lung NK cells show a clear phenotypical activation and maturation in response to IAV infection that increased from days 3 to 4 post infection." (PMID 29497422, 2018). "To examine whether LEC stimulation would activate resting T cells, we measured cell activation markers CD25, CD69, and HLA-DR in LEC stimulated resting T cells on day 6 post infection." (PMID 30285810, 2018). "Infection did not affect the percentages of CD4+ T cells positive for interleukin-4 (IL-4) or the activation marker CD69; however, it increased percentages of IL-17A+ CD4+ T cells by 4.0-fold." (PMID 28442605, 2017). "Interestingly, after infection (43 dpi), a high proportion of antigen specific CD4+ T cells expressing CD44 and CD69 were observed in both NGP5B and NGP5B+CPG mice." (PMID 29069089, 2017). "For instance, CD69, CD160, CD44, LAG3, and CTLA-4 expression on day 7 is unaffected in the absence of AT1R following immunization, but here we showed that the expression of these proteins is reduced by day 6 following infection." (PMID 28261571, 2017). "Here, we show that a population with a TRM phenotype (CD8+ CD69+ CD103+) exists in the brain during the chronic stage of infection, and such a population is not confined to endothelial tissues but is observed throughout the brain." (PMID 28424687, 2017). "However, the frequency of cells expressing the activation marker CD69 was increased in the CD56dim αβTCR− (NK CD56dim) and NKT cell populations by day 3 of the trial, 1 day after infection." (PMID 28815218, 2017). "Absolute numbers of CD69+ cNK cells in the spleen did not change after infection with all three strains." (PMID 27721814, 2016). "Thus, we compared the changes in frequency of CD69+ and CD38+ T cells and B cells during infection with parasite burden, to determine if a certain cell type or phenotype was associated with parasite control." (PMID 27662621, 2016). "The expression of the activation marker CD69 and FasR CD95 is in between HIV and HCV mono-infections (closer to HCV mono-infection and closer to HIV mono-infection respectively) but clearly influenced by both HIV and HCV mono-infections for CD69 and CD95 expressions." (PMID 27091211, 2016). "Prior to infection, there was no significant increase in CD69 expression following TCR stimulation for both CD38+ and CD38- CD4+ T cells, although the basal expression of CD69 was higher on CD38+ CD4+ T cells." (PMID 27662621, 2016). "Absolute numbers of CD69+ cNK were increased in the PEC only after cps1-1 infection and not after RH or ME49." (PMID 27721814, 2016). "The up-regulation of CD69 on DN1 T cells was first observed as early as day 11 post-infection in the lung-draining MLN, but not in other tissues examined." (PMID 26652001, 2015). "In line with previous studies 4, 5, 22, IFN‐γ was induced in NK cells within 24 h of nonlethal Py17XNL infection; CD69 and, somewhat surprisingly, CD25 were also induced on NK cells." (PMID 26420375, 2015).
infection (continued). "For example, a significant increase in the percentage of CD69+-expressing NK cells was observed in DENV-infected patients at the early and acute phase of infection (days 1–5 with 29 vs. 13%), maintained at days 6–10 (24 vs. 18%), but decreased after 11 days (13 vs. 5%)." (PMID 24860571, 2014). "Both CD8+/CD69+ and CD4+/CD69+ T cells were significantly elevated early in infection." (PMID 24658451, 2014). "To analyze the effect of cellular activation on non-productive RGH infection we measured CD69 expression, a well characterized early T-cell activation marker, in the different populations of RGH infected cells." (PMID 24502247, 2014). "We demonstrated that CD69 expression peaked at day 2 and remained elevated out to day 5 post-infection (data not shown)." (PMID 24339779, 2013). "Do9432, which showed the highest susceptibility to HIV replication, expressed high levels of CD86 and CD69 in the absence of infection." (PMID 24341794, 2013). "Treatment with losartan or captopril was started immediately after infection, in a dose at least 10 or 20 times above the IC50 for Captopril (IC50 = 1.940 mg/Kg/d) or Losartan (IC50 = 0.966 mg/Kg/d), respectively in relation to CD69 expression." (PMID 23646169, 2013). "CD69 expression was increased in semen T cells by SIV infection, at all stages of infection." (PMID 24348253, 2013). "Moreover, the upregulation of the activated markers CD69, CD44, CD40L, and the downregulation of CD62L were observed in the CD4+ and CD8+ T cells following infection." (PMID 23555767, 2013). "On the other hand, we have shown that allogeneic co-culture of mDC and CD4+ T lymphocytes induced higher levels of CD69 and CD25 expression and proliferation, independently of the presence of HIV-1, and that it resulted in higher viral trans-infection and replication in CD4+ T cells." (PMID 23590845, 2013). "During the course of infection, these peripheral DP cells acquire an activated phenotype similar to what is described for activated and memory single-positive T cells with high IFN-γ production, CD44+CD69+ expression, and cytotoxic activity." (PMID 22518275, 2012). "cLN analyzed at 12 hours post-infection demonstrated no increase in CD69, CD80, or CD86 under any conditions (data not shown)." (PMID 22393351, 2012). "We also evaluated the expression of CD69 by B220+ B and CD4+ T cells after infection with LP-BM5." (PMID 22691411, 2012). "Interestingly, we observed an increase in the proportion of CD69+ cells in the BAL as early as 24 hours post-infection, and nearly 60% of BAL CD4+ T cells were CD69+ at 48 hours." (PMID 21647373, 2011). "During the course of experimental infection, these peripheral DP cells acquire an activated phenotype similar to what is described for activated and memory single-positive T cells with high IFN-γ production, CD44+CD69+ expression and cytotoxic activity." (PMID 21858238, 2011). "Remarkably, B cells in infected TLR7-deficient mice upregulated CD69 and CD86 early in infection, but failed to develop into germinal center B cells." (PMID 21998589, 2011). "CD25 and CD69 expression on CD4+ and CD8+ T cells each peaked between weeks 3 and 4 post-infection." (PMID 20714351, 2010). "Moreover, while CD69 expression returned to levels observed in naïe mice by day 3, the ability of splenocytes to lyse YAC-1 targets remained elevated until 5 days post-infection." (PMID 17407097, 2007). "This showed that although on day 7 p.i. there were more lymphocytes recruited to lungs infected with v-176WT compared with infection with vH1 or v176-NHA, CD3+ T cells were less activated, and this was reflected by a lower level of the activation marker CD69+ on both CD4+ and CD8+ lymphocytes." (PMID 17485525, 2007).
infection (continued). "We focused our analysis on CD69-, CD38-, CD25-, and HLA-DR-expressing CD4 T cells, along with CD69- and CD38-expressing CD8 T cells, whose frequency increased consistently across all donors upon infection with at least one strain (compared to the uninfected control)." (PMID 40162896, 2025). "The decrease of memory B cells, CD69+ and CD38+T cells, as well as the increase of PD-1+, CTLA-4+ of CD4+/CD8+T cells and double negative B cells, indicate that sustained immune responses against BA.5 infection may wane more rapidly in elderly populations." (PMID 40416973, 2025). "Furthermore, the increase in the frequency of IFN-γ-secreting, antigen-specific CD103+CD69+CD8+ T cells in the lung, supports the notion that sequential infection promotes the generation of tissue-resident memory T cells with enhanced cytokine secretion capacity in IN-vaccinated mice." (PMID 39356719, 2024). "CD69 is one of the early activation in the cells, the higher level of it in TLR3 KO mice may mainly reflect that the absence of TLR3 signaling trigger mechanisms early activation status during infection." (PMID 38172683, 2024). "CD69 is a marker of resident memory in resting lymphocytes, but is recognized as a marker of lymphocyte activation in non-resting states such as acutely after infection." (PMID 38715601, 2024). "This may be attributed to the robust activation of CD8 T cells in the non-infected condition, as evidenced by the elevated expression of CD69 on T cells in the absence of infection." (PMID 38425844, 2024). "Similarly, for KM12 target cells, vBiKE treatment after 36 h coculture triggered stronger NK cell degranulation in the MV-NIS plus CEAxCD16A condition compared to mock infection, even though no increase in CD69 expression was observed on NK cells." (PMID 36765035, 2023). "In addition, treatment of septic animals with HCEPg induced an increase in the CD4+ CD69+ T lymphocyte population, which is impaired in septic pictures with the significant reduction in the number of CD4 T cells, which affects the host response to infection." (PMID 37621924, 2023). "However, only a small percentage of these cells were activated as measured by CD69 expression and they did not appear to offer protection because mice either succumbed to infection or had to be euthanized at this time point." (PMID 37560924, 2023). "To examine whether IEC stimulation would activate resting CD4 + T cells, we measured cell activation markers CD25, CD69, and HLA-DR in IEC-stimulated resting CD4 + T cells on day 6 post-infection using fluorescently labeled antibodies against these markers and flow cytometry." (PMID 37202790, 2023). "Tissue retention in extravascular niches is accomplished in part by surface antigens including CD49a, CD69, and CD103, pathological exert actions are due to bystander activation of parenchymal cells via IFN-γ signaling and through antigen-specific activation, e.g. during re-infection." (PMID 37143648, 2023). "Likewise, CD69+CD4+lo T cell levels (p<0.01) PD-1+CD4+lo T cell levels and (p<0.001) were significantly higher in all infected groups whereas the levels of ICOS+CD4+lo T cells were only significantly higher in chronic HBV (p<0.01) infection." (PMID 37163092, 2023). "The drastic reduction in CD69 expression observed in both SCAT and VAT suggests that even areas of AT not directly infected by SARS-CoV-2 might be altered by the systemic inflammatory responses developed during the infection." (PMID 35661814, 2022). "Importantly, this was not due to preferential infection of a minor pre-existing population of CD69+ CD4+ T cells in blood." (PMID 35417711, 2022). "However, these strategies have not yet been validated and applied in pigs, due to the lack of a specific antibody to pig CD69, hindering the evaluation of the early activation of cellular immunity in pigs during infection or immunization." (PMID 35746813, 2022).
infection (continued). "We observed higher expression of CD38, CD69 and CD40LG during active COVID-19 infection, indicating an activated phase of T cell population, compared to the healthy and the recovered, where the T cells are at resting phase in comparison to the active infection." (PMID 36532041, 2022). "Quantification of CD69 on DN3 cells revealed that, while variable, on average there is a higher level of expression of CD69 on DN3 cells from severe SARS-CoV-2 infection compared to healthy controls, individuals immunized against SARS-CoV-2 and those with mild infection." (PMID 36131937, 2022). "However, for pigs, an anti-pig CD69 antibody is not yet available for this purpose after infection or vaccination." (PMID 35746813, 2022). "Indeed, at 6 weeks post infection, more than 50% of the GFP+ OT-I co-expressed CD69 and CD103." (PMID 35727849, 2022). "Furthermore, surface levels of CD69 in CD4+ and CD8+ T cells were significantly lower in MLNs of mice infected with wild-type Salmonella compared to the steD mutant, indicating that this effect also occurs during natural infection." (PMID 34314469, 2021). "Three studies explored infection with the commensal fungus Candida albicans and showed that Candida albicans can generate long-lived protective CD4+ TRMs in the skin; in particular, the CD4+ CD69+ TRM-like T cells showed increased effector function in response to Candida albicans." (PMID 34445713, 2021). "After spin infection, cells are allowed to rest for 4 days and are treated with the different compounds, as indicated, for 48 h, followed by measurement of HIV-1 LTR-driven luciferase activity and staining for annexin-positive cells and T cell activation markers CD25 and CD69." (PMID 34872356, 2021). "This increase in NK cells appeared to be related to infection because, at baseline, there were minimal differences in the frequency or numbers of NK cells as well as in naïve and effector/effector memory CD4+ T cells or their state of activation at baseline as assessed by CD69 expression." (PMID 32153566, 2020). "The CD8+T cells of non-vaccinated mice responded to challenge infection with an increase in the markers of early activation (CD11a and CD69), and effector (CD62LloCD44hi) or central memory (CD62LhiCD44hi) phenotype but failed to develop polyfunctional cytolytic response." (PMID 31293599, 2019). "Interestingly, γδ T cells that express CD69 and CD103, classically known to provide innate-like protection during primary infection, also provided a significant early-release IL-17 response during secondary infection in convalescent mice." (PMID 30038624, 2018). "As hypothesized, when low levels or no FK506 was added prior to infection, the absence of Vpr resulted in reduced expression of the early activation marker CD69." (PMID 27383627, 2016). "Thus, increased CD69+ cNK cells after RH and ME49 infection could be indicative of increased cNK cell apoptosis." (PMID 27721814, 2016). "However, the percentages of CD1d-α-GalCer-restricted CD4+ cells expressing CD69 in both WT and I-Ab-/- mice were not affected by infection." (PMID 21814579, 2011). "Additionally, CD69 expression intensifies on the NK cell population during infection (not shown), further indicating that the SMG NK cells are capable of recognizing MCMV infection." (PMID 21249177, 2011). "Thus, CD69+ CD103+ mLN Trm are not uniformly generated in response to infection, suggesting that the respiratory route of infection may be critical for these populations." (PMID 34143731, 2021). "Moreover, these fewer CD4+ and CD8+ T cells displayed reduced expression of activation markers such as CD69 and LFA1, consistent with data in spleen showing that mTORC1 inhibition of T cells on day 4 prevented T cell activation and trafficking to the brain later in infection." (PMID 29121917, 2017).
infection (continued). "Further, more recent evidence suggests CD69 may directly influence the development of Treg CD4+ T cells, enhance differentiation of Th17 cells, and regulate TGF-beta secretion, and thus may play a major role in regulating immune responses to infections such as SIV/HIV." (PMID 22096538, 2011). "For example, the relative abundance of CD8 T cells expressing both CD69 and CD103 increased with time, then decreased, while CD8 T cells expressing CD69 but not CD103 were rapidly lost in the second week post infection, and then stabilized." (PMID 40060443, 2025). "Raphin1 treatment did not improve kidney function in nephritic wild-type mice in which CD4+CD69+ TRM cells were not induced by infection, indicating that CD4+CD69+ TRM cells were required for the therapeutic effect." (PMID 40050432, 2025). "Further, CD8+ T cells in the lung and spleen of BC-colonized GF mice expressed significantly higher levels of CD69, IFN-γ and granzyme B compared with those from noncolonized GF mice following IAV PR8 infection at 8 dpi." (PMID 39388633, 2024). "IAV-specific CD4 T cells in the lung did not display increased expression of CD69, ICOS, or Ifnγ following re-infection." (PMID 37842651, 2023). "Numbers of CD8+ and CD4+ T-lymphocytes expressing CD69 and TRM markers were significantly increased 1 mo after infection with Lm 10403s, but not Δhly Lm mutants." (PMID 37143648, 2023). "DN2 cells from severely infected SARS-CoV-2 subjects had significantly higher levels of CD69 expression, but not CD86, when compared to individuals immunized against SARS-CoV-2 or those with mild infection." (PMID 36131937, 2022). "Consistent with the findings in acute infection-induced TRM33,47,48, the induction of CD69 was reduced, but not completely abolished in Tgfbr2−/− cells." (PMID 36229613, 2022). "Lung and airway CD69+CD103+ CD8+ T cells were i.v.-, i.e., not binding anti-CD45 in the circulation, and peaked at day 4 post re-infection." (PMID 35108347, 2022). "Early treated individuals exhibited a non-significant dip in CD69 expression on monocytes, compared to HIV uninfected persons, with a recovery to pre-infection levels by 12-months post-infection." (PMID 34630420, 2021). "On the one hand, CD69+ NK cells have been shown to increase in the bone marrow of mice and peaked 72 h MHV-3 post-infection which would support our observations that no acute immune responses were present at the time of analysis." (PMID 33879187, 2021). "A large pool of TRM cells was induced, as the majority of the OT-I T cells in the lungs expressed the typical TRM markers CD69 and CD103 four weeks post infection, but no sizeable KLRG1+ population was detected." (PMID 33479479, 2021). "In contrast to cytokines and NK cells, the frequency of activated CD69+ CD4+ and CD38+ CD8+ T cells remained higher in the convalescent phase, regardless of infection symptomatic or asymptomatic nature, compared to healthy controls." (PMID 34669281, 2021). "M.tb MOI 1 and MOI 5 infection, as well as PPD stimulation, but not PM2.5 exposures, significantly increased CD69 expression in all PBMC T cell subsets compared to control PBMC." (PMID 31731429, 2019). "The induction of lung NK cell CD69 expression was, however, not fully TLR7-dependent, as significant CD69 expression was also detected in TLR7ko NK cells by day 4 post infection." (PMID 29497422, 2018). "Despite expressing moderately high levels of CD69, untreated CD4+ T cells isolated from tonsillar tissue did not give rise to significantly higher levels of productive infection (0.68%) compared to CD4+ T cells from peripheral blood." (PMID 26067822, 2015). "Although not statistically significant a similar trend of increased CD69 expression was noted on CD4+ T cells at day 14 and day 28 post-infection." (PMID 26322025, 2015).